AIM2 (absent in melanoma 2)
Diseases named in the same sentence as AIM2 in open-access papers (continued):
Sharing a sentence is not in itself a finding about the gene and the disease.
colon carcinoma (continued). "Hypermethylation of the AIM2 promoter conferred insensitivity to IFN-γ-induced AIM2 expression of MSI-H colon cancer cell lines, demonstrating the inactivation of AIM2 was regulated by epigenetic factors." (PMID 36118867, 2022). "Meanwhile, AIM2 inhibited colon cancer cell proliferation by inducing cell cycle arrest in the G2/M phase." (PMID 36248785, 2022). "An inflammasome‐independent pathway of AIM2 has also been discovered, controlling intestinal cell proliferation, apoptosis, and metastasis in the regulation of colon cancer through suppression of AKT activation." (PMID 34014039, 2021). "Still further, AIM2 has been reported as exhibiting tumour-suppressive functions in colon cancer by suppressing the PI3K/AKT pathways to inhibit proliferation of colonic stem cells and promote cell death." (PMID 33614494, 2020). "Further studies also support the tumor suppressor role of AIM2 in several types of tumors, including colon cancer, breast cancer, and prostate cancer." (PMID 27167192, 2016). "Recent work in colon cancer indicated that AIM2 restricted proliferation of colon cancer cells by reducing the activation of AKT pathway, which helps to understood its tumor suppressor function in colon cancer." (PMID 27167192, 2016). "Furthermore, AIM2’s inflammasome-independent role in inhibiting colon cancer is mediated by the suppression of DNA-dependent protein kinase (DNA-PK) activation and Akt signaling pathways." (PMID 40692785, 2025). "CCK8 and colony formation assays indicated that the knockdown of AIM2 could significantly promote colon cancer proliferation." (PMID 37932362, 2023). "Transwell assay showed that the inhibition of AIM2 could remarkably enhance the invasion and migration ability of colon cancer cells." (PMID 37932362, 2023). "We also note that an inflammasome‐independent role for AIM2 that is intrinsic to the gut epithelium has been demonstrated in colon cancer, whereby AIM2 suppresses intestinal tumorigenesis in ApcMin/+ and DSS/AOM mouse models by modulating intestinal epithelial cell apoptosis and proliferation." (PMID 36967659, 2023). "The positive correlation of AIM2 to these cells might partly explain the anticancer effect of AIM2 in colon cancer." (PMID 37932362, 2023). "Subsequently, we sought to investigate the role of AIM2 in colon cancer." (PMID 37932362, 2023). "Taken together, our data suggested that AIM2 inhibits BRAF-mutant colon cancer growth in a caspase-1-dependent manner, which may provide evidence to understand the pathogenesis of CRC with BRAF-mutant, as well as new strategies for manipulation of CRC." (PMID 33842454, 2021). "Indeed, tumor‐suppressive properties of AIM2 have been identified in hepatocellular carcinoma, renal carcinoma, breast cancer, colon cancer, HPV‐infected cervical carcinoma, and prostate cancer." (PMID 34014039, 2021). "This suggests that AIM2 is required to restrain the progression of colon cancer." (PMID 34014039, 2021). "The high levels of AIM2 expression in intestinal epithelial cells in response to pathogenic infections indirectly inhibit AKT activation, reducing stem cell proliferation in colonic tumors." (PMID 34014039, 2021). "Interestingly, AIM2 has inflammasome-independent roles in mouse models of colon cancer and in Experimental Autoimmune Encephalomyelitis (EAE), a mouse model of multiple sclerosis." (PMID 34854899, 2021). "Moreover, Aim2−/− mice showed increased size and number of colon tumors in a colitis-associated cancer (CAC) model, implying that the AIM2 gene itself regulates tumor progress and prevents colorectal cancer." (PMID 28465544, 2017). "Additionally, our study found that the suppression of AIM2 could significantly enhance the proliferation, invasion, and migration capabilities of colon cancer cells." (PMID 37932362, 2023). "Previous studies have shown that AIM2 significantly inhibits the PI3K/AKT pathway, which has been shown to inhibit the development of colon tumors." (PMID 36248785, 2022).
colon carcinoma (continued). "In cancerous colonic epithelial cells AIM2 binds and inactivates the kinase DNA-PK, which is needed for AKT activation and regulates colon cancer progression." (PMID 34854899, 2021). "Therefore, NLRP3 and AIM2 were chose to be detected in in-house GBM samples and publicly available IHC data of colon cancer patients." (PMID 34815793, 2021). "However, the protective action of AIM2 against colon cancer is independent of its inflammasome activation mechanism." (PMID 33643304, 2020). "However, the mechanism by which AIM2 stimulates ISG15 expression in the absence of type I IFNs and the downstream effects of AIM2-induced ISG15 expression and ISGylation in colon cancer cells are unclear." (PMID 27626310, 2016).
Stroke (34 papers, 2015 to 2025). Sudden impairment of blood flow to a part of the brain due to occlusion or rupture of an artery to the brain. "We focused on these two abundant inflammasome subtypes, because the NLRP3 inflammasome has previously been implicated in the development of atherosclerosis, whereas stroke leads to systemic AIM2 inflammasome activation." (PMID 39112714, 2024). "In the middle cerebral artery occlusion (MCAO)-induced PSCI mouse model, AIM2 expression was upregulated in microglia and endothelial cells, correlating with cognitive deficiency observed at 28 days post-stroke." (PMID 39684321, 2024). "The AIM2 inflammasome mediates post-stroke immunosuppression, which predisposes individuals to systemic infections." (PMID 37216118, 2023). "Experimental stroke causes DNA damage, where AIM2 inflammasomes are the main inflammasomes involved in DNA damage, and NLRC4 can form inflammasomes involved in regulating host immune and inflammatory responses." (PMID 36034843, 2022). "A detrimental role for AIM2 in CNS pathologies is further supported by the observation that AIM2 deficient mice show less brain atrophy and cognitive defects following stroke than their wild type counterparts." (PMID 33042875, 2020). "AIM2 inflammasome-mediated pyroptosis could cause acute and chronic neuronal death after stroke, which might result in cognitive dysfunction." (PMID 37332874, 2023). "It remains controversial which cell types are impacted by AIM2 inflammasome activation in the CNS after stroke." (PMID 39854137, 2025). "Clinical studies have shown a significant increase in the number of penumbral AIM2+/CD68+ cells in stroke patients." (PMID 40351418, 2025). "Collectively, these results suggested that 3‐HKA promotes vascular remodeling after stroke by transforming A1‐like into A2‐like astrocytes through impeding AIM2 inflammasome activation." (PMID 39854137, 2025). "Targeting NET formation or AIM2 inflammasome activation represents a potential therapeutic strategy for attenuating post-stroke neuroinflammation and secondary neuronal damage." (PMID 40479571, 2025). "Proteomic analysis revealed that 3‐HKA inhibited AIM2 inflammasome activation after stroke, and co‐labeling studies indicated that AIM2 expression typically increased in astrocytes at 7 and 14 days after stroke." (PMID 39854137, 2025). "In animal models of stroke and cell models of oxygen‒glucose deprivation/reperfusion, the AIM2 inflammasome is significantly activated, and this is accompanied by neuronal pyroptosis." (PMID 40351418, 2025). "To further verify the mechanism by which 3‐HKA inhibits the activation of the AIM2 inflammasome after stroke, we also examined the mRNA expression of other Nod‐like receptors, such as NLRP3, NLRP1a and NLRC4." (PMID 39854137, 2025). "Compared with the sham group, the AIM2 protein levels were increased following stroke, and the increased AIM2 protein levels were reversed by 3‐HKA treatment." (PMID 39854137, 2025). "Correspondingly, research had demonstrated that the activation of the AIM2 inflammasome in astrocytes, microglia, macrophage, and neutrophil contributed to a pro-inflammatory response, thereby worsening stroke conditions." (PMID 39600708, 2024). "Rapid neutrophil NETosis was identified as the main source of cell-free DNA after stroke and NET–DNA as the causative agent leading to AIM2 inflammasome activation." (PMID 39112714, 2024). "Of the finally enrolled 127 patients, 56 consented for blood-collection at multiple time points and constituted a special group for uncovering dynamic change of serum AIM2 levels after stroke." (PMID 38714826, 2024). "In summary, we identified the activation of the AIM2 inflammasome in vulnerable atherosclerotic plaques by stroke-induced DNA release and subsequent plaque rupture as the cause of recurrent ischaemic events." (PMID 39112714, 2024).
Stroke (continued). "Emerging evidence suggests that the AIM2 inflammasome plays a critical role in the pathogenesis of post-stroke cognitive impairment (PSCI) through inflammatory processes and pyroptosis." (PMID 39684321, 2024). "Our results suggest that future randomized controlled trials are warranted to evaluate the safety and efficacy of targeting NETs, AIM2, or IL-1β for improved stroke outcomes." (PMID 39737165, 2024). "Here, using a novel mouse model of stroke-induced recurrent ischaemia, we show that stroke leads to activation of the AIM2 inflammasome in vulnerable atherosclerotic plaques via an increase of circulating cell-free DNA." (PMID 39112714, 2024). "Noteworthily, our study showed that serum AIM2 levels in patients were significantly higher than those in healthy controls, and this increase lasted until at least 10 days after the onset of stroke." (PMID 38714826, 2024). "As for predictive ability for DCI, AUCs of serum AIM2 levels at 1, 2, 3, 5, 7 and 10 days after stroke were 0.758 (0.634–0.887), 0.762 (0.615–0.874), 0.770 (0.588–0.854), 0.682 (0.530–0.810), 0.665 (0.513–0.796) and 0.661 (0.508–0.792) respectively." (PMID 38714826, 2024). "A151 treatment resulted in reduced expression of cGAS, AIM2, IL-1β and IL-18 after experimental stroke and decreased infarct volume and improved neurological deficits after stroke." (PMID 37212886, 2023). "Our previous study revealed that AIM2 deletion inhibited microglial infiltration 48 h after stroke and protected against ischemic brain injury." (PMID 37177836, 2023). "Taken together, AIM2 plays a pivotal role in the local neuroinflammatory as well as the systemic immune response to stroke." (PMID 37212886, 2023). "We have previously demonstrated that AIM2 inflammasome activation by cfDNA release after stroke and burn injury leads to IL-1β release." (PMID 37212886, 2023). "AIM2 drives inflammation to worsen ischemic brain injury and mediates post-stroke immunosuppression by induction of T cell death." (PMID 37216118, 2023). "Previous studies have reported that AIM2 affects cognitive function in diseases such as AD, stroke and vascular dementia." (PMID 37177836, 2023). "Although AIM2 is essential for normal human brain development, it also exacerbates the inflammatory response during stroke." (PMID 37165005, 2023). "Recent results have demonstrated that AIM2 is also crucial in mediating the systemic inflammatory response to stroke." (PMID 37212886, 2023). "Here, AIM2 was mainly expressed in Iba-1 + microglia, but also in the endothelium and neurons with a peak of AIM2 expression 3 days after experimental stroke." (PMID 37212886, 2023). "Binding of post-stroke double-strand cfDNA to AIM2 leads to increased blood IL-1β concentrations, which results in apoptosis of circulating lymphocytes." (PMID 37212886, 2023). "We have previously shown that the release of cfDNA from dying tissue or activated neutrophils leads to a rapid systemic AIM2-mediated inflammasome activation and subsequent increased levels of circulating IL-1β after stroke." (PMID 37212886, 2023). "In the present study, we demonstrated that THSWD attenuated mitochondrial DNA and nuclear DNA damage during stroke; reduced AIM2, NLRC4, and Caspase-1 inflammasomes; and inhibited IL-1β and IL-18 inflammatory factor release after IS." (PMID 36034843, 2022). "Here we found a significant increase in the mRNA levels of Tak1 and the inflammasomes Nlrp3, Nlrc4, and Aim2 after stroke compared to sham surgery." (PMID 34628598, 2022). "Compared to the sham/control group, a higher intensity of AIM2+/caspase‐1+ staining in the hippocampus and cortex was observed in the stroke/control group (7 days post stroke)." (PMID 35076161, 2022). "Similar to these results, our PBM with 630‐nm LED arrays, especially in the acute phase of stroke, attenuated AIM2 inflammasome activation and mediated pyroptosis in the injured regions, improving spatial learning and memory." (PMID 35076161, 2022).
Stroke (continued). "TAK1 is reported to regulate the activation of the NLRP3 inflammasome but little is known about the influence of TAK1 on NLRP3, NLRC4, and AIM2 inflammasomes after stroke." (PMID 34628598, 2022). "Conclusively, we showed that the receptors of NLRP3, NLRC4, and AIM2, the executors of Caspase-1 and−11 were the main contributors of-post stroke inflammasome activation, which participated in the production of IL-1β, IL-18, and GSDMD." (PMID 33967935, 2021). "That is, the roles of NRLP1, NRLP3, NRLP4 and AIM2 inflammasomes in stroke, and its outcome, were determined via various in vitro and in vivo settings." (PMID 34112082, 2021). "Kim and colleagues described that the AIM2 inflammasome contributes to brain injury and chronic post-stroke cognitive impairment in mice." (PMID 32645874, 2020). "Instead, NLRC4 and AIM2 along with ASC were suggested to be the major contributors to brain injury in the MCA occlusion (MCAO) model of stroke in mice, as further evidenced by others as well." (PMID 32635451, 2020). "The difference in AIM2 localization among studies may be related to differences in the time points evaluated and the stroke models used." (PMID 39854137, 2025). "We found that AIM2 was co‐localized mainly with astrocytes, a few neurons and endothelial cells, with almost no co‐localization with microglia at days 7 and 14 after stroke." (PMID 39854137, 2025). "In both BV2 cells and stroke-induced mice, NETs triggered AIM2-dependent pyroptosis." (PMID 40479571, 2025). "Both the inhibition of AIM2 and NLRP3 prevented inflammasome activation in the CCA plaque after stroke, with greater efficacy of the AIM2 inhibitor, whereas only the AIM2 inhibitor significantly prevented the post-stroke increase in IL-1β levels in the CCA plaque." (PMID 39112714, 2024). "The AIM2 inflammasome activation led to excessive T cell death to aggravate stroke disease." (PMID 39600708, 2024). "The 4-sulfonic calixarenes inhibited AIM2-dependent post-stroke T cell death, highlighting a proof of concept that the 4-sulfonic calixarenes could be effective at combating post-stroke immunosuppression." (PMID 37216118, 2023). "Our previous study found that AIM2 could activate microglia‐related inflammation in experimental stroke." (PMID 37177836, 2023). "A post-stroke increase in AIM2 expression was also found after experimental stroke in rats." (PMID 37212886, 2023). "Consequently, treatment with 4-sulfonic calixarenes attenuates post-stroke immune alterations including AIM2-dependent post-stroke immunosuppression." (PMID 37212886, 2023). "In addition, AIM2‐mediated inflammation and pyroptosis likely aggravate poststroke cognitive impairment, and AIM2 knockout significantly improves cognitive function and reverses the decrease in hippocampal volume in stroke mice." (PMID 37177836, 2023). "Consequently, the authors concluded that the AIM2 inflammasome controls inflammation and pyroptosis after stroke." (PMID 37450925, 2023). "In addition, the deleterious effect of AIM2 on ischemic brain injury has also been shown in rodent models of stroke." (PMID 36034843, 2022). "Further, we also evaluated whether brain PBM therapy in the acute phase of stroke attenuates the development of PSCI by controlling AIM2 inflammasome activation and the inflammatory response." (PMID 35076161, 2022). "However, immuno-reactivities neither in neurons (NeuN) nor in astrocytes (GFAP) were detected, suggesting that microglial or endothelial cell-induced AIM2 production mediated post-stroke cognitive impairment pathogenesis." (PMID 32645874, 2020). "E2 or P selectively mitigated the stroke-induced increase of AIM2 and NLRC4." (PMID 32645874, 2020). "Accordingly, NLRP1 and AIM2 were present in the clots of nine patients with stroke." (PMID 33569001, 2020). "Similarly, using a rodent model of stroke, a study showed that Aim2 inflammasome activation contributes to brain injury." (PMID 31771614, 2019).